CBX3 (chromobox 3)
Diseases named in the same sentence as CBX3 in open-access papers (continued):
Sharing a sentence is not in itself a finding about the gene and the disease.
cancer (52 papers, 2006 to 2026). A tumor composed of atypical neoplastic, often pleomorphic cells that invade other tissues. "Recent studies underlined the mechanisms through which CBX3 inhibitors can exert their effects, including the modulation of specific biochemical pathways that govern cancer cell proliferation." (PMID 39272883, 2024). "Recent research has revealed that CBX3 is intricately linked with glutamine metabolism, a vital process for rapidly proliferating cells, including cancer cells." (PMID 39272883, 2024). "Further, the expression of CBX3 triggers the development of stem cell-like characteristics in lung tumors, enhancing the presence of markers associated with cancer stem cells and targets of the oncogenic transcription factor c-Myc." (PMID 39272883, 2024). "Due to its cancer-causing properties, CBX3 shows potential as a reliable predictive biomarker and a possible target for treatment in NSCLC associated with smoking." (PMID 39272883, 2024). "Based on this premise, CBX3 has been found implicated in a broad spectrum of human cancers, including NSCLC." (PMID 39272883, 2024). "Very recently, gene amplification emerged as a potential mechanism that underlies CBX3 overexpression in human cancer and consequently as a poor prognosis marker in NSCLC." (PMID 37633946, 2023). "In contrast, KIRC and high expression of CBX3 were linked to reduced step-5 activity (infiltration of immune cells into malignancies)." (PMID 37674204, 2023). "Our results first suggested that CBX3 expression was significantly associated with the TILs and cancer—associated fibroblast in certain tumors." (PMID 35172803, 2022). "Here, we show for the first time that high CBX3 expression associates with cancer dedifferentiation status and CBX3HIGH tumors exhibit the cancer stem cell-like phenotype." (PMID 36361869, 2022). "This further supports our first observation of positive association between CBX3 and cancer stemness." (PMID 36361869, 2022). "We further confirmed a robust enrichment of CBX3-associated transcriptome profiles with several hallmarks of cancer previously identified as upregulated in stemness-high tumors." (PMID 36361869, 2022). "In our data, the most prominent and consistent positive association with cancer stemness was observed for CBX3." (PMID 36361869, 2022). "CBX3 was found to be significantly associated with the clinical cancer stage and short DFS in CRC patients." (PMID 33014884, 2020). "Chromebox protein homolog 3 (CBX3) as a member of the heterochromatin-associated protein 1 (HP1) family has been reported to be overexpressed in human cancer tissues." (PMID 33273987, 2020). "In view of the growing correlation between immunological features and cancer prognosis, we then examined the association between TIICs and CBX3 in LUAD." (PMID 32894652, 2020). "CBX3 was significantly associated with the clinical cancer stage and short disease-free survival (DFS) in CRC patients." (PMID 33014884, 2020). "Specifically, CBX1 and CBX3 play a crucial role in heterochromatin formation, gene silencing, and DNA damage response and have been implicated in various cellular processes, including cell cycle regulation and cancer progression." (PMID 40175347, 2025). "Moreover, we demonstrated for the first time that K10la is essential for maintaining CBX3 interaction with H3K9me3 and further regulates cancer hallmark process‐gene expression and GI progression." (PMID 39018247, 2024). "In this report, we showed for the first time that CBX3 gene amplification strongly co-occurs with both EGFR and RAC1 genes in different human cancers and that this molecular event is associated with an increase of mRNA and protein levels of CBX3, EGFR and RAC1." (PMID 37633946, 2023). "As a predisposing factor, these toxic chemicals, may induce cancer by affecting CBX3 or its binding genes." (PMID 35172803, 2022).
cancer (continued). "Moreover, CBX3 overexpressing tumors manifest higher frequencies of genomic alterations, which strongly reflects the elevated mutation burden of cancer stem cell-like tumors." (PMID 36361869, 2022). "Aberrant CBX3 expression has been implicated in the development of various cancer types." (PMID 34785774, 2022). "Similar to high-stemness tumors, CBX3-overexpressing cancers manifest a higher mutation load." (PMID 36361869, 2022). "Moreover, the CBX3 expression is strongly linked to the level of immune invasion and immune-related genes in human pan-cancer, especially in ACC, MESO, LUAD, LIHC, LGG, HNSC, and PAAD." (PMID 35573019, 2022). "In addition, except as a protective factor in THYM, CBX3 appeared to be a risk factor in other cancer types." (PMID 35172803, 2022). "Additionally, we explored the potential association between genetic alteration of CBX3 and the clinical survival prognosis of cases with different types of cancer." (PMID 35172803, 2022). "CBX3 is associated with the epigenetic regulation of cell differentiation and cancer development." (PMID 31138312, 2019). "HP1γ, encoded by CBX3, is associated with cancer progression and patient prognosis." (PMID 31375643, 2019). "We found that CBX3/HP1γ was upregulated in many cancers and was associated with poor prognosis." (PMID 31375643, 2019). "Chromobox protein homolog 3 (CBX3) is a heterochromatin protein that is upregulated in various tumors and can epigenetically regulate crucial genes for cancer development and growth." (PMID 40100307, 2025). "High expression of CBX3 has been found in various cancers, where it functions as an oncogene by regulating multiple biological processes in cancer cells." (PMID 39636180, 2024). "It has been observed that CBX3 promotes lung tumorigenesis by interacting with cancer-specific pathways, leading to increased cell proliferation and survival." (PMID 39272883, 2024). "Future research should focus on delineating the regulatory networks involving CBX3 and exploring the therapeutic implications of targeting its interactions to restore apoptotic pathways and inhibit cancer cell proliferation." (PMID 39272883, 2024). "Numerous studies have demonstrated that CBX3 played significant roles in various cancers by regulating multiple mechanisms including heterochromatin formation, gene silencing and DNA replication." (PMID 39636180, 2024). "These inhibitors are proposed as molecularly targeted therapeutics, aiming to disrupt the pathways through which CBX3 contributes to cancer progression." (PMID 39272883, 2024). "These strategies collectively emphasize the need for innovative drug development efforts focused on CBX3, aiming to enhance treatment specificity and effectiveness while overcoming resistance barriers in cancer therapy." (PMID 39272883, 2024). "Given the pivotal role of CBX3 in cancer metabolism, targeting CBX3-related pathways presents a promising therapeutic strategy." (PMID 39272883, 2024). "Consistent with TCGA pan‐cancer data, our proteomics data indicated that the abundance of CBX3 was globally elevated in GI cancers." (PMID 39018247, 2024). "By inhibiting the Notch pathway, one can potentially disrupt the self-renewal and survival mechanisms of cancer stem cells, thereby enhancing the efficacy of CBX3 targeting." (PMID 39272883, 2024). "Current strategies for developing CBX3 inhibitors have garnered significant attention due to their potential in addressing drug resistance and improving cancer treatment outcomes." (PMID 39272883, 2024). "Here we describe that a wide spectrum of human cancers harbors a co-amplification of CBX3 gene with either EGFR or RAC1, which yields a statistically significant increase of both mRNA and protein levels of CBX3, EGFR and RAC1." (PMID 37633946, 2023). "By querying cBioportal and TCGA databases, we selected data from some human cancers with the highest frequency of CBX3 gene amplification." (PMID 37633946, 2023).
cancer (continued). "Growing evidence indicates that CBX3 is crucial for the incidence, progression, and prognosis of numerous kinds of cancers, including ccRCC." (PMID 37674204, 2023). "Chromobox Protein 3 (CBX3) overexpression is a common event occurring in cancer, promotes cancer cell proliferation and represents a poor prognosis marker in a plethora of human cancers." (PMID 37633946, 2023). "Recently, the oncogenic role of CBX3 has been identified in various malignant tumors and serves as a prognostic and immunological biomarker." (PMID 37762371, 2023). "Taken together, the first pan-cancer analyses of CBX3 indicated statistical correlations of CBX3 expression with survival prognosis, DNA methylation, protein phosphorylation, immune cell infiltration across multiple tumors." (PMID 35172803, 2022). "In this part, we investigated the potential relationship between the infiltration level of different immune cells and CBX3 gene expression or clinical outcome in diverse cancer types of TCGA." (PMID 35172803, 2022). "To evaluate the CBX3 expression in pan-cancer, we utilized R software to jointly assess the RNA sequencing data in both the GTEx and TCGA." (PMID 35573019, 2022). "Overall, the results showed that genic and proteinic terms of CBX3 were overexpressed in most cancers." (PMID 35172803, 2022). "Our results clearly demonstrate yet unrecognized association of high CBX3 and low CBX7 expression with cancer stem cell-like phenotype of solid tumors." (PMID 36361869, 2022). "Our data indicate that CBX3 also facilitates cancer stemness, although direct mechanism remains elusive." (PMID 36361869, 2022). "We first used the DNMIVD and CPTAC datasets to explore the CBX3 methylation and phosphorylation expression level across all TCGA cancers." (PMID 35172803, 2022). "The relationship between human CBX3 (NM_007276.4 for mRNA or NP_009207.2 for protein) and pan-cancer was explored from many aspects in the study." (PMID 35172803, 2022). "Based on the results, we aimed to investigate the value as a biomarker and to evaluate the potential molecular mechanism of CBX3 in different cancers." (PMID 35172803, 2022). "Increased evidence supports the relationship between chromobox protein homolog 3 (CBX3) and tumorigenesis of some cancers." (PMID 35172803, 2022). "CBX3 was reported to play an important role in cell growth in some cancer types, however, it is role in OV is still unclear." (PMID 35155439, 2022). "Many studies have reported elevated expression of CBX3 in different human cancer tissues and proposed it as a predictor of unfavorable prognosis for malignancies." (PMID 36292141, 2022). "In this study, we found that abnormal expression of CBX3 existed in human pan-cancer, including BRCA, COAD, PAAD, UCEC, and LUAD." (PMID 35172803, 2022). "According to the expression levels of CBX3, the cancer cases were divided into high-expression and low-expression groups." (PMID 35172803, 2022). "The first pan-cancer study offers a relatively comprehensive cognition on the oncogenic roles of CBX3 as a prognostic and immunological marker in various malignant tumors." (PMID 35172803, 2022). "For instance, patients showed more invasion and aberrant prognosis subtype (C1, C2, C4) as CBX3 was up‐regulated in pan‐cancer." (PMID 33463006, 2021). "This meta-analysis was designed to explore the relationship between CBX3 expression and clinical data in patients with malignant tumors." (PMID 33273987, 2020). "In conclusion, existing studies have demonstrated that CBX3 is highly expressed in a variety of cancers and predicts a poor prognosis for malignancy." (PMID 33273987, 2020). "In recent years, many studies have described that CBX3 is upregulated in various malignant tumors and is closely related to the prognosis of cancer patients." (PMID 33273987, 2020). "After more in-depth mechanism researches, CBX3 is expected to be an effective prognostic biomarker and therapeutic target for cancer patients." (PMID 33273987, 2020).
cancer (continued). "The expression of CBX3 was positively associated with the infiltration of CD8+ T cells and macrophages in the two cancer types." (PMID 33014884, 2020). "Chromobox protein homolog 3 (CBX3) has been involved in the regulation of gene transcription, and it is upregulated in many cancer types." (PMID 32682359, 2020). "The role of CBX3 in cancer prognosis and clinicopathological characteristics was assessed by pooled hazard ratios (HRs) and odds ratios (ORs) with 95% confidence intervals (CIs)." (PMID 33273987, 2020). "This growing evidence identified CBX3 as an essential molecule in the tumorigenesis and treatment of human cancers." (PMID 32742466, 2020). "Numerous studies have shown the relationship between the CBX3 expression and clinicopathological factor or prognosis in malignant tumors, but their results are inconsistent." (PMID 33273987, 2020). "CBX3/HP1γ mRNA expression levels were examined in various cancers using the Oncomine and Human Protein Atlas databases." (PMID 31375643, 2019). "CBX3/HP1γ regulates gene expression via epigenetic silencing, and previous studies have demonstrated that up-regulation of CBX3/HP1γ occurs in a variety of cancers." (PMID 31375643, 2019). "Some recent studies have identified the expression and role of CBX3 in different type of human cancers." (PMID 29903985, 2018). "The result showed that high expression of CBX3 in PAAD tissues predicted a poor prognosis of cancer patients in overall survival." (PMID 29903985, 2018). "Combining CBX3 inhibitors or modulators with existing cancer therapies could potentially enhance therapeutic efficacy." (PMID 39272883, 2024). "This resistance indicates that CBX3 may play a pivotal role in mediating treatment efficacy and underscores the importance of personalized therapy in combating cancer." (PMID 39272883, 2024). "CBX3 has been found to be dysregulated showing an abnormal expression profile in various cancers." (PMID 39272883, 2024). "CBX3 is able to interfere with the functioning of this pathway, and its effect may vary depending on the specific cellular environment and cancer type." (PMID 39272883, 2024). "On the other hand, cancer samples from TCGA Pan Cancer Atlas Studies harboring high CN increase of CBX3 display enhanced expression of EGFR at the transcriptional level, further confirming the tight relationship between the CNVs occurring in CBX3 and EGFR genes in human cancer." (PMID 37633946, 2023). "CBX3 is a component of heterochromatin, and plays important roles in cancers." (PMID 37436074, 2023). "It has been also hypothesized that the oncogenic variant of the epidermal growth factor receptor (EGFR), a well-known proto-oncogene widely overexpressed and/or amplified in human cancer, may be correlated with CBX3 expression in NSCLC." (PMID 37633946, 2023). "Next, we set out to check whether the co-amplification of CBX3 with either EGFR or RAC1 genes might affect cancer aggressiveness and patient lifespan." (PMID 37633946, 2023). "We can thus argue that the co-occurrence of CBX3 and RAC1 gene amplification might be a way to increase RAC1 and CBX3 expression during cancer development, two well-known proteins that have been linked to cancer growth and proliferation when overexpressed." (PMID 37633946, 2023). "Therefore, it is necessary to evaluate the correlation between CBX3 and the characters of immune infiltration in pan-cancer." (PMID 35172803, 2022). "Here, we verified whether the CBX3- and CBX7-associated gene expression profiles reflects the enrichment with specific hallmarks of cancer observed in mRNA-SI." (PMID 36361869, 2022). "Nowadays, CBX3 has obtained widespread attention as a potential biomarker in several cancers." (PMID 35172803, 2022).
cancer (continued). "Results showed CBX3 expression impacted patients’ PFI in 12 cancer types." (PMID 35172803, 2022). "We tried to explore the protein expression patterns of CBX3 in cancers by the Human Protein Atlas." (PMID 35172803, 2022). "Mechanically, several miRNAs have been reported to regulate the expression of CBX3 in cancer." (PMID 36140750, 2022). "Increasing research has reported the roles of CBX3 in cancer development." (PMID 36140750, 2022). "In this study, we conducted a pan-cancer analysis of CBX3 based on multiple databases." (PMID 35172803, 2022). "We evaluated the effect of CBX3 expression on prognostic value for the patients in pan-cancer." (PMID 35172803, 2022). "We applied the TIMER2.0 tool to analyze the expression of CBX3 in cancers of TCGA." (PMID 35172803, 2022). "The genetic variation of CBX3 in various cancer samples were observed via the cBioportal tool." (PMID 35172803, 2022). "Some literature reported that CBX3 was related to immunity in specific cancers." (PMID 35172803, 2022). "None of the existing studies has focused on the relationship between CBX3 and pan-cancer." (PMID 35573019, 2022). "On this account, CBX3 may potentially be of great importance in the epigenetic regulation of cancer development." (PMID 35172803, 2022). "Further studies are needed to determine whether epigenetic functions mediated by Cbx3/HP1γ and Cbx7 are sufficient to promote cancer stemness." (PMID 36361869, 2022). "CBX3 is upregulated in many cancers and plays an important role in the progression of tumors." (PMID 34722422, 2021). "The results of this meta-analysis indicated that CBX3 expression may be a novel biomarker for predicting patient prognosis and clinicopathological parameters in multiple human cancer." (PMID 33273987, 2020). "It should be noted that CBX3 not only plays a crucial role in the development and progression of malignant tumors but also becomes a reliable prognostic indicator and potential target therapeutic site for cancer patients." (PMID 33273987, 2020). "In the present study, we explored the expression and prognostic significance of CBX3/HP1γ in cancer patients using the Oncomine, Cancer Genome Atlas (TCGA) and Human Protein Atlas databases, the UALCAN interactive web-portal, and the Kaplan–Meier plotter survival analysis platforms." (PMID 31375643, 2019). "Little is known about the function of CBX-3 in cancer cells." (PMID 31565104, 2019). "Most cancer tissues showed moderate to strong nuclear expression of CBX3/HP1γ." (PMID 31375643, 2019). "CBX3 has been observed to mediate various cellular action in different cancer cells." (PMID 29903985, 2018). "Heterochromatin protein 1γ (CBX3) links histone methylation marks to transcriptional silence, DNA repair and RNA splicing, but a role for CBX3 in cancer remains largely unknown." (PMID 28193906, 2017). "Furthermore, the exploration of combination therapies involving CBX3 inhibitors is gaining momentum, as these strategies may enhance therapeutic efficacy by synergizing with established cancer treatments." (PMID 39272883, 2024). "Therefore, combining Notch signaling inhibitors with CBX3 targeting could enhance therapeutic outcomes by simultaneously attacking the cancer from multiple angles." (PMID 39272883, 2024). "As this field of research evolves, emerging trends and potential biomarkers for identifying patients most likely to benefit from CBX3 inhibitors are becoming increasingly relevant, paving the way for innovative treatment paradigms that could significantly impact cancer care." (PMID 39272883, 2024). "The evidence that this gene co-amplification occurs in different human cancers could suggest a functional relationship between CBX3, EGFR and RAC1 genes which normally occurs in physiological conditions but that could promote cancer progression when dysregulated." (PMID 37633946, 2023). "However, the role of CBX3 in pan-cancers remains poorly defined." (PMID 35172803, 2022).